JAK2 (Janus kinase 2)
Diseases named in the same sentence as JAK2 in open-access papers (continued):
Sharing a sentence is not in itself a finding about the gene and the disease.
rosacea (2 papers, 2024 to 2025). A chronic erythematous skin disorder that affects the face. "In rosacea, we found that the JAK2/STAT3 signaling pathway is significantly activated in mast cells and LL37-induced skin lesions." (PMID 41383625, 2025). "LL37 induces activation of the TLR2/JAK2 pathway in mast cells of rosacea-like mice." (PMID 41383625, 2025). "In summary, our study identifies the TLR2/MyD88/JAK2/STAT3 signaling pathway as a critical mediator of mast cell activation and degranulation in rosacea." (PMID 41383625, 2025). "By elucidating the intricate interplay between LL37, TLR2, and JAK2/STAT3 signaling in mast cells, our findings provide novel mechanistic insights into rosacea pathogenesis and lay the groundwork for the development of targeted therapies." (PMID 41383625, 2025). "In this study, we showed that ruxolitinib, a JAK2 inhibitor, effectively alleviates erythema and inflammation in an LL37-induced mouse model of rosacea." (PMID 41383625, 2025). "Furthermore, we show that pharmacological inhibition of JAK2 using ruxolitinib effectively attenuates LL37-induced mast cell activation, offering a potential therapeutic strategy for rosacea." (PMID 41383625, 2025).
Salmonella Infections (2 papers, 2016 to 2025). Infections with bacteria of the genus SALMONELLA. "The addition of clove extract and eugenol effectively inhibited the excessive activation of the JAK2/STAT3 signaling pathway induced by Salmonella infection (P < 0.05)." (PMID 40059168, 2025). "Salmonella infection led to the overactivation of the JAK2/STAT3 signaling pathway." (PMID 40059168, 2025). "Therefore, we can conclude that the dephosphorylation of both JAK2 and NF-κB found via our kinomic analysis is indicative of a negative regulation of a pro-inflammatory response; in this case brought about by the establishment of a persistent Salmonella infection." (PMID 27472318, 2016).
scleroderma (2 papers, 2022 to 2023). Scleroderma is a rare autoimmune connective tissue disorder characterized by abnormal hardening of the skin and, sometimes, other organs. "Our study indicates that the JAK1 and JAK2 inhibitor has stronger antifibrotic effects than the JAK3 inhibitor, and JAK2 inhibitor use also results in the loss of capillaries in BLM-induced scleroderma mice." (PMID 35733864, 2022). "JAK1 and JAK2 but not JAK3 inhibitors alleviated skin fibrosis in different aspects, such as morphology and dermal thickness, and the JAK2 inhibitor alleviated skin fibrosis the most, demonstrating that JAK inhibition prevented fibrosis in a BLM-induced mouse model of scleroderma." (PMID 35733864, 2022).
serous ovarian cancer (2 papers, 2016 to 2022). "Cell lysates from human serous ovarian cancer were subjected to western blot to measure endogenous JAK2 and STIP1 protein expression." (PMID 35269562, 2022). "Significantly positive correlations between STIP1 and JAK2 expression in serous ovarian cancers were identified (P < 0.05)." (PMID 27409672, 2016). "Finally, expression of STIP1 and JAK2 were positively correlated to each other in human serous ovarian cancer specimens." (PMID 35269562, 2022).
severe combined immunodeficiency (2 papers, 2016 to 2018). Severe combined immunodeficiency (SCID) comprises a group of rare monogenic primary immunodeficiency disorders characterized by a lack of functional peripheral T lymphocytes resulting in early-onset severe respiratory infections and failure to thrive. "We also use the Jak2 structure to demonstrate how Jak3 mutations identified in patients result in severe combined immunodeficiency (SCID)." (PMID 27227461, 2016). "For example, mutant Jak1 and Jak3 mice have severe combined immunodeficiency (SCID), and Jak1 mutants also have neurological defects and poor survival past birth; knock out mutations in Jak2 are embryonic lethal, and mutations in the Jak family member Tyk2 result in poor response to pathogens." (PMID 30558204, 2018).
Shock (2 papers, 2010 to 2022). The state in which profound and widespread reduction of effective tissue perfusion leads first to reversible, and then if prolonged, to irreversible cellular injury. "As a result, mice deficient for Jak2 show a DC-dependent resistance to lethal dose of LPS-induced septic shock, a deadly disorder caused by the excessive innate immune response." (PMID 20231889, 2010). "It was unveiled that the lack of JAK2 selectively repressed DCs-regulated innate immunity in mice with LPS-induced septic shock by playing an important role in the development and maturation of DCs while also regulating DC secretion of proinflammatory cytokines." (PMID 35710633, 2022).
skin cancer (2 papers, 2022 to 2024). "Although the role of AFs and IL-6 in skin cancer has not been extensively studied, our findings show that prenatally AFs release IL-6, which promotes the phosphorylation of JAK2 and STAT3 in KSCs." (PMID 38519574, 2024).
subarachnoid hemorrhage (2 papers, 2013 to 2021). A serious neurological disorder characterized by intracranial hemorrhage into the subarachnoid space. "In addition, the therapeutic effect of recombinant human erythropoietin (rhEPO) on the subsequent vasospasm after subarachnoid hemorrhage may relate to its inhibition of endothelial apoptosis in cerebral arteries, which may be mediated in part by the JAK2/STAT3 signaling pathway." (PMID 23483946, 2013).
Uterine leiomyoma (2 papers, 2023 to 2025). The presence of a leiomyoma of the uterus. "Activation of JAK2/STAT3, MAPK/ERK, and PI3k/Akt pathways have previously been linked to the binding of leptin, an adipocyte derived hormone, to Ob-R; however, the effect of adipocyte coculture on uterine leiomyoma cells remained a gap in knowledge." (PMID 36771423, 2023). "For the first time, we demonstrated the amplified activation of JAK2/STAT3, MAPK/ERK, and PI3k/Akt because of adipocyte coculture along with leptin treatment in uterine leiomyoma cells." (PMID 36771423, 2023). "Further investigation into the effect of MAPK/ERK, JAK2/STAT3, and PI3k/AKT inhibitors in adipocyte-mediated leiomyoma growth could lead to viable therapeutic strategies for uterine leiomyomas." (PMID 36771423, 2023). "The upregulation of the JAK2/STAT3, MAPK/ERK, and PI3k/Akt pathways impacts several pathways integral to cell growth and metabolism and implicates adipose tissue as having a role in the cancerous uterine leiomyoma growth." (PMID 36771423, 2023).
Wernicke encephalopathy (2 papers, 2022 to 2025). An acute neurological disorder characterized by the triad of ophthalmoplegia, ataxia, and disturbances of mental activity or consciousness. "Fedratinib—an anticancer agent inhibiting Janus kinase 2 (JAK2)—blocks the essential intestinal thiamine transporter THTR2 and plays a crucial role in the onset of Wernicke’s encephalopathy." (PMID 40243711, 2025). "Fedratinib, a Janus kinase 2 (JAK2) inhibitor used as an anticancer drug, inhibits crucial intestinal thiamine transporter THTR2 and contributes to the development of Wernicke ́s encephalopathy." (PMID 35276844, 2022).
Zinc deficiency (2 papers, 2021 to 2022). A deficiency of the essential metal Zinc; an essential cofactor for many enzymes. "The present study investigated whether zinc deficiency induces leptin secretion by activating a JAK2/STAT3 signaling pathway and leads to osteoblastic apoptosis." (PMID 36615735, 2022). "To examine whether zinc deficiency could affect the interactions of STAT3 with JAK2 and the phosphatases PTP1B and SHP2, we immunoprecipitated STAT3 from E19 CT and did immunoblotting for the interacting proteins." (PMID 34049221, 2021). "Taken together, results support the concept that an impairment of PTP1B degradation could be one of the mechanisms underlying zinc deficiency-mediated deactivation of the JAK2/STAT3 signaling pathway during early brain development." (PMID 34049221, 2021).
acne (1 paper, 2025). An inflammatory process of the sebaceous glands which is characterized by comedones, nodules, papules and/or pustules on the skin. "Previous research has demonstrated that JAK is overexpressed in common acne lesions, suggesting that combined JAK1 and JAK2 inhibitors could potentially be therapeutic for acne." (PMID 40860887, 2025).
Adenovirus infection (1 paper, 2026). "Adenovirus infection can cause inflammation and upregulation of the JAK/STAT pathway, ultimately leading to increased mRNA levels of IL-6, IL-1 β and IFN - α, as well as increased levels of JAK2, STAT3, p-JAK2 and p-STAT3 protein bands." (PMID 41399758, 2026).
allergic rhinitis (1 paper, 2021). Inflammation of the nasal mucous membranes caused by an IgE-mediated response to external allergens. "Thus, further study is needed to investigate whether YJD could alleviate allergic rhinitis via regulating Wnt/β-catenin or JAK2/STAT3 signaling pathways." (PMID 34315133, 2021).
anal squamous cell carcinoma (1 paper, 2021). A squamous cell carcinoma (SCC) arising from the anal canal or the anal margin (perianal skin). "However, it is notable that loss of STAT1, JAK2, and CD274 was detected in a patient with HPV18-positive anal squamous cell carcinoma who did not benefit from treatment." (PMID 34446728, 2021).
anaphylaxis (1 paper, 2025). An acute hypersensitivity reaction that occurs from exposure to an allergen. "Since JAK2 contributes to the pathogenesis of allergic airway inflammation, it will be necessary to examine whether JAK2 inhibitors can suppress anaphylaxis." (PMID 40005151, 2025).
ankylosis (1 paper, 2018). Fixation and immobility of a joint. "In this study, we demonstrated the mechanism by which IL-17-mediated JAK2 activation leads to osteoblast differentiation and bone formation; this mechanism may be similar to that of ankylosis progression." (PMID 29880011, 2018).
aortic valve disorder (1 paper, 2024). A disease involving the aortic valve. "UKBB data revealed a positive correlation between the JAK2 V617F somatic variant and aortic valve disease (effect size 0.0086, p = 0.85) and TAA (effect size = 0.004, p = 0.92), although not statistically significant." (PMID 39062663, 2024). "Our analysis identified a small positive effect of the JAK2 V617F variant on nonrheumatic aortic valve disorders (effect size = 0.05) and aortic valve disease (Effect Size = 0.0086)." (PMID 39062663, 2024).
Arrhythmia (1 paper, 2024). Any cardiac rhythm other than the normal sinus rhythm. "We further found a larger accumulation of interstitial fibrosis, increased TGF-β expression in HFD hearts, and direct stimulation of JAK2-induced arrhythmias." (PMID 39063055, 2024). "Overactivation of IL-6 trans-signaling in guinea pigs prolonged the QT interval, which resulted in greater susceptibility to arrhythmias/SCD with isoproterenol challenge, as also observed with the downstream Janus kinase (JAK) 2 activator." (PMID 39063055, 2024).
Atrophy (1 paper, 2023). Any weakening or degeneration, especially through lack of use. "Exo-miR-214 can significantly inhibit the expression level of PTEN, increase the protein expression levels of p-JAK2 and p-STAT3 and the ratio of p-JAK2/JAK2 and p-STAT3/STAT3, also MDSCs-derived exosomes with overexpressed miR-214 can reduce the occurrence of denervated muscle atrophy." (PMID 37305554, 2023).
autoimmune thyroiditis (1 paper, 2025). "Total glucosides of paeony (TGP) can regulate the expression of SOCS1 in rats with autoimmune thyroiditis, enhance the expression of JAK1, JAK2, STAT3, and STAT5, thereby affecting the JAK/STAT signaling pathway." (PMID 40584613, 2025).
Azoospermia (1 paper, 2024). Absence of any measurable level of sperm,whereby spermatozoa cannot be observed even after centrifugation of the semen pellet. "A recent study on patients affected by azoospermia showed a possible link between azoospermia and JAK2 expression." (PMID 38900205, 2024).
behavioral disorders (1 paper, 2025). "Taken together, these results suggest that the JAK2/STAT3 signaling pathway may act as a downstream target in response to a miR‐204‐5p deficiency, thereby contributing to the neuronal injury and behavioral disorders observed in these rats." (PMID 39792918, 2025). "In specific, we show that a miR‐204‐5p deficiency contributes to the enhancement of neuroinflammation and apoptosis involved with the pathogenesis of behavioral disorders via activating its downstream target, the JAK2/STAT3 signaling pathway, which then promotes neuronal deterioration in rats." (PMID 39792918, 2025).
Blindness (1 paper, 2022). Blindness is the condition of lacking visual perception defined as a profound reduction in visual perception. "Cytokines, which utilize Janus kinase 2 (Jak2) for signaling, drive the inflammatory processes in ERU that promote blindness." (PMID 35505065, 2022).
bone cancer (1 paper, 2024). A primary or metastatic malignant neoplasm affecting the bone or articular cartilage. "Recent studies have suggested that the JAK2/STAT3 pathway is abnormally activated in different forms of chronic pain, including neuropathic pain, inflammatory pain, morphine tolerance and bone cancer pain." (PMID 37307838, 2024).
Bovine mastitis (1 paper, 2025). INFLAMMATION of the UDDER in cows. "JAK-2 is one of the key members in JAK-STAT signaling pathway and the activation of this gene is critical in bovine mastitis resistance." (PMID 40936092, 2025).
calcification (1 paper, 2022). Process by which organic tissue becomes hardened by the physiologic deposit of calcium salts. "It was also suggested that this suppressive effect was induced by the Janus kinase 2 (JAK2)/signal transducer and activator of transcription 3 (STAT3) pathway, and that adiponectin may have an important role in the treatment of vascular calcification." (PMID 36289903, 2022).
central obesity (1 paper, 2022). "Janus kinase 2 (JAK2) is associated with central obesity and increased waist circumference." (PMID 36439174, 2022).
cerebellar tumor (1 paper, 2021). "The patient had a history of PV with Janus Kinase 2(JAK2) V617F mutation and was initially suspected to have a cerebellar tumor." (PMID 34134639, 2021).
cervical disease (1 paper, 2019). "To look at the correlation of JAK2, STAT3 and STAT5 phosphorylation in cervical disease, we plotted the normalized intensities of phosphorylated JAK2 against that of phosphorylated STAT3 and phosphorylated STAT5 from CIN 3, which represents pre-cancerous lesions." (PMID 31817106, 2019). "First, we utilised the cervical liquid-based cytology samples representing pre-cancerous cervical disease progression (CIN1-3) and normal cervical tissue as shown for JAK2." (PMID 31817106, 2019). "The data shows that JAK2, STAT3 and STAT5 phosphorylation correlates with cervical disease progression." (PMID 31817106, 2019).
childhood cancers (1 paper, 2020). "Abnormalities in six genes (NRAS, ABL1, JAK2, KIT, ALK and BRAF) were common in childhood cancers as well as adult cancers, for which at least one approved drug could be a potentially actionable drug." (PMID 33051474, 2020).
chordoma (1 paper, 2025). Chordomas are rare malignant tumors arising from embryonic remnants of the notochord in axial skeleton. "In summary, our data indicate that chordoma cells require JAK-STAT signaling driven by TBXT, particularly JAK2, suggesting an immediately applicable strategy for targeted treatment of patients with chordoma using clinically approved JAK2 inhibitors." (PMID 40901948, 2025). "When testing drugs that target this pathway on different levels, we found a dependence of chordoma cells on JAK2." (PMID 40901948, 2025). "This is also supported by the fact that we observed strong interferon signaling in cell lines and patients with chordoma and that JAK2 inhibition with fedratinib inhibited the growth of patient-derived chordoma organoids." (PMID 40901948, 2025). "Finally, we found high interferon signaling in chordoma cell lines and patient tumors, which was promoted by TBXT and associated with sensitivity to JAK2 inhibitors." (PMID 40901948, 2025).
chronic obstructive pulmonary disease (1 paper, 2024). A chronic and progressive lung disorder characterized by the loss of elasticity of the bronchial tree and the air sacs, destruction of the air sacs wall, thickening of the bronchial wall, and mucous accumulation in the bronchial tree. "Moreover, the patient suffered from polycythemia vera with V617F JAK2 mutation, diabetes mellitus, chronic kidney disease, and chronic obstructive pulmonary disease (COPD)." (PMID 39544101, 2024).
chronic thromboembolic pulmonary hypertension (1 paper, 2024). Chronic thromboembolic pulmonary hypertension (CTEPH) is characterized by the persistence of thromboemboli in the form of organized tissue obstructing the pulmonary arteries. "The involvement of the JAK/STAT cascade in inflammation and fibrosis in lung tissue has driven studies on the use of the JAK1 and JAK2 inhibitor ruxolitinib in chronic thromboembolic pulmonary hypertension." (PMID 39684570, 2024).
Chuvash polycythemia (1 paper, 2025). Chuvash erythrocytosis is a rare, genetic, congenital secondary polycythemia disorder characterized by increased hemoglobin, hematocrit and erythropoietin serum levels and normal oxygen affinity, which usually manifests with headache, dizziness, dyspnea and/or plethora. "They found that Chuvash polycythemia-associated VHL variants do not cause the ubiquitin-mediated breakdown of the activated JAK2 protein." (PMID 40130200, 2025).
clear cell carcinoma (1 paper, 2018). "In this study, we explored the activation of JAK2/STAT3 pathway in serous HEY and clear cell carcinoma TOV21G cell lines in vitro by Western Blot and immunofluorescence in response to the concentration of paclitaxel which inhibited cell growth by 50% (GI50) (HEY: 0.05ng/mL, TOV21G: 0.01ng/mL)." (PMID 29682172, 2018).
clear-cell ovarian cancers (1 paper, 2020). "A Japanese study found that p-STAT3 expression was correlated with OS, and the activation of the JAK2/STAT3 pathway is critical for the survival of clear-cell ovarian cancers." (PMID 33029256, 2020).
cleft palate (1 paper, 2023). Cleft palate is a fissure type embryopathy that affects the soft and hard palate to varying degrees. "Further investigation to identify individuals with an increased risk of preventable cleft palate is warranted, and mouse models are indispensable for improving our understanding of the JAK2/STAT3 axis." (PMID 37846594, 2023). "In conclusion, our findings provide new evidence of JAK2/STAT signaling involvement in the fusion of the secondary palate and the genetic etiology of the cleft palate." (PMID 37846594, 2023). "Thus, our findings suggested the function of JAK2/STAT3 in palatal fusion and also provided experimental basis for the beneficial use of folic acid for cleft palate." (PMID 37846594, 2023).
CNS leukemia (1 paper, 2022). "Of the 7 children with CNS leukemia, 1 was JAK2+, 1 was FLT3+, and 1 was MUC16+." (PMID 35733807, 2022).
cystic fibrosis (1 paper, 2013). Autosomal recessive disorder caused by pathogenic variants in the CFTR gene (cystic fibrosis transmembrane conductance regulator), which encodes a chloride and bicarbonate channel expressed in epithelial cells, and follow the diagnosis criteria. "We selected three peripheral blood specimens submitted to our molecular pathology laboratory for testing with either the Cystic Fibrosis Genotyping Assay, a quantitative JAK2 V617F MutaQuant assay, or our laboratory-developed Fragile X syndrome assay." (PMID 23862106, 2013).
cystic kidneys (1 paper, 2026). "We observed that the overexpression of CFB in cystic kidneys was associated with increased Janus kinase 2 (JAK2)/signal transducer and activator of transcription 1 (STAT1) activity and enhanced expression of the polycystin-1 C-terminal tail (PC1-CTT)." (PMID 41431718, 2026).